RNU6-82P (RNA, U6 small nuclear 82, pseudogene)
Synonyms: RNU6-82
Gene: Small nuclear RNA gene on chromosome 13 (28,232,501 to 28,232,607, forward strand). Ensembl gene ENSG00000200840.
Homologues: Orthologues: chimpanzee U6 (99% identical), dog U6 (80% identical), rabbit U6 (80% identical), mouse Gm55093 (73% identical), rat LOC120095376 (73% identical), guinea pig U6 (66% identical). Paralogues in human: RNU6-589P (85% identical), RNU6-259P (83% identical), RNU6-946P (83% identical), RNU6-1330P (82% identical), RNU6-214P (82% identical), RNU6-224P (81% identical), RNU6-28P (81% identical), RNU6-43P (81% identical), RNU6-647P (81% identical), RNU6-737P (81% identical), RNU6-761P (81% identical), RNU6-832P (81% identical), and 1285 more.